PLK1 (polo like kinase 1)
Diseases named in the same sentence as PLK1 in open-access papers (continued):
Sharing a sentence is not in itself a finding about the gene and the disease.
neuroblastoma (continued). "NPM1 function is regulated primarily through phosphorylation by PLK1, that leads to the protection from cell death; Indeed, the inhibitor of PLK1, that induces apoptosis, is used in the treatment of several cancers, including esophageal cancer, neuroblastomas, and others." (PMID 27326393, 2016). "AURKA and PLK1 are up-regulated by MYCN and are frequently overexpressed in MYCN-amplified neuroblastomas." (PMID 33194665, 2020). "Similar results were found in Versteeg-88 dataset including 88 neuroblastoma samples, demonstrating that PLK1 could be served as a potential predictor in NB patients' outcome." (PMID 32231733, 2020). "In the present study, we have evaluated and screened the efficacy of the NF-kB/mTOR dual inhibitor 13-197, PLK1 inhibitor BI2536 and hedgehog pathway inhibitor vismodegib alone or in combination with topotecan against neuroblastoma." (PMID 26934655, 2016). "Several cell cycle regulators, such as PLK1, TRIM16, WEE1, CDK4/6, and CCND1, have been shown to be involved in the tumorigenesis of neuroblastoma." (PMID 26225123, 2015). "This evidence is consistent with the finding that PLK1 inhibition by volasertib leads to the stabilization of the ubiquitin ligase Fbxw7 and the degradation of its downstream target N-Myc in MYCN-overexpressing neuroblastoma cells." (PMID 36902175, 2023). "Some of the dual inhibitors targeting pBRD4 and PLK1, PI3K, ALK, HDAC, p38α, and CDK9, were reported to have a strong downregulation effect on c-Myc or N-Myc in acute myeloid leukaemia, neuroblastoma, castration-resistant prostate cancer, pancreatic cancer, hepatocellular, and colorectal carcinoma." (PMID 36902175, 2023). "PLK-1, CDK-1, PIK3CA, ATF4, TEAD4 and ALYREF could enhance MYCN protein stability and sustain MYCN expression in neuroblastoma." (PMID 35820898, 2022). "Our current study demonstrated that PLK1 was highly expressed in neuroblastoma cells, and its expression level was independent of the MYCN status." (PMID 32231733, 2020). "Inhibitors of PLK1, such as BI6727 and BI2356, preferentially trigger apoptosis of MYCN-amplified neuroblastoma and small cell lung cancer, and this therapeutic efficacy is synergistically enhanced by combined use with antagonists of anti-apoptotic B cell lymphoma 2 (BCL2)." (PMID 33614505, 2020). "Mitotic kinases, such as Aurora kinase A (AURKA) and Polo-like kinase 1 (PLK1), are reported to stabilize MYCN by inhibiting the Fbxw7-mediated degradation of the MYCN protein and may promote SCD in MYCN-amplified neuroblastoma cells." (PMID 33194665, 2020). "Importantly, MYCN-amplified tumor cells in neuroblastoma and small cell lung cancer are more sensitive to treatment with PLK1 inhibitors than tumors with normal MYCN copy number, indicating that PLK1 inhibitors are potential therapeutics for MYCN-overexpressing cancers." (PMID 33628735, 2020). "Polo-like kinase 1 (PLK1) is an essential cell cycle mitotic kinase component that plays an important role in cell cycle progression and has been reported to be involved in various cancers, including neuroblastoma (NB)." (PMID 35631350, 2022). "However, the impact of GSK461364 on Myc is not yet well understood, as phenotypic effects from PLK1 inhibition, which are not dependent on MYCN amplification status, have been reported in neuroblastoma cell lines." (PMID 36902175, 2023).
leukemia (32 papers, 2013 to 2025). A malignant (clonal) hematologic disorder, involving hematopoietic stem cells and characterized by the presence of primitive or atypical myeloid or lymphoid cells in the bone marrow and the blood. "GW843682X is also a novel selective PLK1 inhibitor which caused accumulation of cells in the G2/M phase and mediated apoptosis of human leukemia cells." (PMID 25574601, 2015). "For example, Aurora kinases and PLK1 are upregulated in human leukemia cell lines and patient samples with AML and other myelodysplastic syndromes." (PMID 38308077, 2024). "Our study shows that blocking the PLK-1 signaling pathway by using the PLK-1 inhibitor volasertib is a particularly effective treatment strategy in infant MLLr leukemia." (PMID 39684470, 2024). "By using RNA-seq and RT-qPCR, we revealed PLK-1 was specifically upregulated in MLLr leukemia derived from infant cells in comparison to healthy but also adult leukemic cells." (PMID 39684470, 2024). "The PLK-1 mRNA level was significantly increased in our huCB compared to the huBM model, which was underpinned by analyzing infant and adult MLLr leukemia patients." (PMID 39684470, 2024). "Polo-like kinase 1 (PLK1), which is involved in cell cycle control, was effectively inhibited in vivo using a patient-derived leukemia in mice with improvement in extramedullary disease." (PMID 36900239, 2023). "Overexpression of PLK1 has been found in multiple types of solid tumors as well as in leukemia, and correlated with poor prognosis and survival." (PMID 35156101, 2021). "For example, 17p loss increases resistance to seven different drugs in leukaemia (LAML) and five of these target cell cycle/mitotic regulators (KIF11, CDK2/7/9, WEE1, PLK1, microtubules)." (PMID 31974379, 2020). "RGS has been described to inhibit PLK1-activity, thereby inducing G2/M arrest in leukemia cells, but the exact mechanism of action was elusive." (PMID 29423069, 2018). "We investigated the inhibitory effects of PLK1 on Ph-positive leukemia cells by examining the effects of PLK1 siRNA knockdown in K562 cells." (PMID 26008977, 2015). "We found that the PLK1 protein was highly expressed in leukemia cell lines as well as 73.3% (11/15) of pediatric acute myeloid leukemia (AML) samples." (PMID 25574601, 2015). "The efficacy of our PLK1 inhibitor NMS-P937 in this model supports its clinical development in leukaemias." (PMID 23520509, 2013). "PLK1 is an attractive target in cancer, since it is overexpressed in a variety of solid tumours and in some leukaemias, most prominently in." (PMID 23520509, 2013). "To further elucidate the potential mechanism of TCP1-mediated AML cell survival, we analyzed its regulatory effects on PLK1 (a cell cycle regulator) and AML1-ETO (a leukemia-associated fusion protein) using AML cell lines with constitutive TCP1 knockdown (HL-60-G4-shTCP1 and Kasumi-1-shTCP1)." (PMID 40430849, 2025). "In summary, our findings suggest that the PLK-1 pathway may be of particular significance, especially in the context of infant MLLr leukemia." (PMID 39684470, 2024). "By using a variety of pharmaceutical assays, we were able to demonstrate the superior anti-leukemic effect of volasertib in infant in contrast to adult leukemia; we revealed a higher PLK-1 expression in our infant MLLr model and commercially available cell lines (THP-1, SEM)." (PMID 39684470, 2024). "Therefore, we assessed the impact of KIFC1 inhibitors, as well as inhibitors of the mitotic kinases, aurora kinase A (AURKA) and polo-like kinase 1 (PLK1), on 2 primary Eμ-Ret leukemia samples and the 289 cell line." (PMID 38519798, 2024). "However, although the blocking of PLK-1 was generally well tolerated, the results, especially as monotherapy, were hampered by limited clinical success in adult leukemia patients." (PMID 39684470, 2024).
leukemia (continued). "In addition, although it has not been completedly translated to clinical trials, a specific PLK1 inhibitor, onvansertib, has shown good tolerance and efficacy in combination therapy with decitabine for leukemia treatment." (PMID 33588776, 2021). "Specific PLK1/PLK1 knockdown on both protein and mRNA level is achieved by short interfering Ribonucleic Neutrals (siRNNs) as pro-drugs which can be cleaved intracellularly into short interfering ribonucleic acids (siRNAs) as demonstrated in leukemia." (PMID 34065956, 2021). "RO3280 was recently identified as a novel PLK1 inhibitor; however its therapeutic effects in leukemia treatment are still unknown." (PMID 25574601, 2015). "Therefore, we first examined PLK1 expression in Ph-positive leukemia cells and observed expression in Ph-positive leukemia cell lines and primary samples as well as cluster of differentiation (CD) 34-positive CML samples." (PMID 26008977, 2015). "However, one of the top candidates responsible for PLK-1 re-upregulation in adult leukemia cells upon volasertib treatment was Aurora kinase A. A number of Aurora kinase A inhibitors have already shown convincing results, for example, alisertib, which is currently undergoing clinical evaluation." (PMID 39684470, 2024). "Therefore, high PLK1 levels are a marker of cellular proliferation in cancers such as leukemia." (PMID 26008977, 2015). "Inhibition of Plk1 activity by the Plk1 inhibitors volasertib effectively reduced the phosphorylation of AKT, mTOR and S6 in leukemia and Burkitt lymphoma cells." (PMID 40166466, 2025). "Among the commonly used PLK1 inhibitors, BI6727 has been recognized by the FDA as an innovative therapy for leukemia." (PMID 39763588, 2024). "In leukemia, this drug induces mitotic catastrophe in chronic myelogenous leukemia (CML) cells via JNK-dependent inhibition of Plk1 expression and triggers apoptosis by a caspase 2-mediated mechanism." (PMID 35734412, 2022). "Unfortunately, there were no data on childhood leukemia available, but this highlights the oncogenic and pivotal role of PLK-1 in leukemogenesis and as a potential target." (PMID 39684470, 2024). "Strikingly, we identified PLK-1 as a driver of infant but not adult MLLr leukemogenesis, suggesting it as a potential promising targeted therapy approach in this subtype of MLLr leukemia." (PMID 39684470, 2024). "PLK1 is also known as an oncoprotein in leukemia and ranked by MUFFINN (42nd) yet not by three gene-centric methods (below 9000th) in LAML samples." (PMID 27333808, 2016). "Therefore, the higher expression of PLK-1 and the absence of this escape mechanism in MLLr cells derived from huCB could serve as an explanation for the better response to volasertib in infant MLLr leukemia." (PMID 39684470, 2024). "PLK1 and PLK4 expression levels are higher in leukemia cells than in non-tumorous cells and have promise as being new targets for cancer therapy." (PMID 35256538, 2022).
acute myeloid leukemia (31 papers, 2015 to 2026). Acute myeloid leukemia (AML) is a group of neoplasms arising from precursor cells committed to the myeloid cell-line differentiation. "For instance, the study titled " PLK1 inhibition induces synthetic lethality in Fanconi anemia pathway-deficient acute myeloid leukemia ", published on March 20, 2025, emphasized the significance of the PLK1-FANCD2 interaction in cancer metabolism." (PMID 41542076, 2025). "Association of polo-like kinase 1 (PLK1) expression with clinico-pathological characteristics in 105 pediatric acute myeloid leukemia (AML) samples." (PMID 25574601, 2015). "Whereas, the PLK1 mRNA expressions were lower in acute myeloid leukemia (LAML) and thyroid carcinoma (THCA)." (PMID 36618405, 2022). "Volasertib, a selective PLK1 inhibitor, was effective for acute myeloid leukemia (AML) patients in clinical trials." (PMID 29108241, 2017). "Volasertib (BI6727) was the first PLK1 inhibitor to be tested clinically has reached phase III for the treatment of acute myeloid leukemia (AML)." (PMID 26799423, 2016). "PLK1 is also highly expressed in leukemic cell lines and over expressed in a majority of samples from patients with acute myeloid leukemia compared with normal progenitors." (PMID 25574601, 2015). "On the other hand, in esophageal squamous cell carcinoma (ESCC) and acute myeloid leukemia (AML) cells there was an opposite correlation between mTOR and PLK1 in autophagy." (PMID 35719948, 2022). "In addition, analysis of publicly available data from acute myeloid leukemia (AML) patients showed a trend towards decreased overall survival in adult leukemia cases with higher PLK-1 expression, which extended beyond those with MLL fusions." (PMID 39684470, 2024). "The most successful Plk1 inhibitor, volasertib (BI6727), reached phase III clinical trials for adult acute myeloid leukemia patients ineligible for intensive remission induction therapy." (PMID 32060361, 2020). "Another PLK-1 inhibitor, BI 6727 or volasertib in combination with low-dose cytarabine is being studied in a phase III trial in patients with acute myeloid leukemia, after encouraging results in a phase II trial." (PMID 26754547, 2016). "Finally, we detected the cleavage of Plk1 in three other cell lines, JURLMK1, another CML cell line, SKM1 an MDS/AML (myelodysplastic syndrome/acute myeloid leukemia) cell line and U266, a multiple myeloma cell line." (PMID 29541386, 2018). "Importantly, one PLK1 inhibitor, Volasertib (BI6727), has been advanced to phase III clinical trial testing as treatment for acute myeloid leukemia." (PMID 26059434, 2015). "As a low-molecular-weight, ATP-competitive kinase inhibitor, BI6727 effectively inhibits PLK1, PLK2, and PLK3 and has shown promising effects in various xenograft models and patients with acute myeloid leukemia (AML) (Gjertsen and Schöffski, 2015)." (PMID 39763588, 2024). "Evaluation of this PROTAC, HBL-4, in a model of acute myeloid leukemia (AML) demonstrated rapid degradation of both BRD4 and PLK1." (PMID 37174744, 2023). "These outcomes told us that in the selection process of Plk1 inhibitors for treating tumors, they might not be very suitable for hematological malignant tumors, such as neutropenia, acute myeloid leukemia and non-Hodgkin lymphoma." (PMID 36845678, 2023).
cervical carcinoma (30 papers, 2009 to 2025). A carcinoma arising from either the exocervical squamous epithelium or the endocervical glandular epithelium. "The gene mutation and alteration status of PLK1 in cervical cancer was inspected in COSMIC and cBioPortal databases." (PMID 33354424, 2020). "A total of 12 cases (one case of missense mutation and 11 cases of mRNA low) with genetic alteration of PLK1 were recorded in 190 cervical cancer samples with mutation data from TCGA Firehose project." (PMID 33354424, 2020). "Collection of serum or plasma samples of cervical cancer and non-cancer patients was warranted for appraising diagnostic value of PLK1 for cervical cancer." (PMID 33354424, 2020). "Genetic alteration of PLK1 including missense mutation and mRNA low occurred in 6% of cervical cancer samples profiled in mRNA expression." (PMID 33354424, 2020). "We provide evidence that expression of PLK-1 exists in human cervical carcinoma tissues and establish an association with tumor size." (PMID 19775446, 2009). "Our results, therefore, provided clues that the expression of PLK-1 is associated with the local expansion of cervical carcinoma." (PMID 19775446, 2009). "Finally, the authors concluded that miR-100 participates in the development of cervical cancer at least partly through loss of inhibition to target gene PLK1, which probably occurs in a relative late phase of carcinogenesis." (PMID 24840898, 2014). "Therefore, PLK-1 is implicated as a critical candidate target for understanding the progression of cervical carcinoma and improving chemotherapy." (PMID 19775446, 2009). "Polo-like kinase 1 (PLK1) overexpression in cervical cancer cells is a promising target for developing novel therapies to overcome chemoresistance and improve treatment efficacy." (PMID 40871048, 2025). "Polo-like kinase 1 (PLK1) is overexpressed in cervical cancer cells, linking it to disease progression." (PMID 40871048, 2025). "In particular, volasertib notably suppresses tumor growth in human cervical cancer by inducing cell cycle arrest at the G2/M phase and apoptosis, accompanied by a decrease in PLK1 protein expression." (PMID 40871048, 2025). "In the current study, we aimed at exploring the cell cycle roles of DAPK1 and PLK1 in cervical cancer cells." (PMID 35154442, 2022). "Subsequently, the interaction between endogenous DAPK1 and PLK1 in cervical cancer cells was visualized using the PLA, which depends on recognition of target proteins by pairs of antibody-oligonucleotide conjugates." (PMID 35154442, 2022). "In cervical cancer, PLK1 overexpression was detected using RNA sequence datasets extracted from 290 cervical cancer tissue specimens." (PMID 34830902, 2021). "Collectively, these data indicate that CDK1 and PLK1 represent potential therapeutic targets of GCP in the treatment of cervical cancer." (PMID 34093198, 2021). "The molecular mechanism beneath PLK1 in cervical cancer was further explored via analyzing the genetic alteration profile of PLK1 in cervical cancer and functional enrichment of PLK1-related genes in cervical cancer." (PMID 33354424, 2020). "The methods adopted by those studies of detecting PLK1 expression in cervical cancer were single and there lacks comprehensive evaluation of the clinico-pathological significance of PLK1 in cervical cancer." (PMID 33354424, 2020). "The results from progressive evidence chains constituted of tissue microarrays, IHC, exterior microarrays and RNA-seq dataset indicated PLK1 as a potential biomarker for cervical cancer." (PMID 33354424, 2020). "Remarkably higher expression of PLK1 was observed in all types of cervical cancer patients with lymph node metastasis or CESC patients with lymph node metastasis than in those without lymph node metastasis (X2 = 29.859, P < 0.001; X2 = 29.324, P < 0.001)." (PMID 33354424, 2020).